SLC7A11 (solute carrier family 7 member 11)
Diseases named in the same sentence as SLC7A11 in open-access papers (continued):
Sharing a sentence is not in itself a finding about the gene and the disease.
tumor (continued). "Inhibiting the secretion of PD-L1-based exosome upregulated the IFN-γ level, which aided the downregulation of SLC3A2 and SLC7A11, two subunits to maintain the cysteine uptake by tumor cells." (PMID 34593794, 2021). "The level of CD44 can regulate the sensitivity of tumor cells to ferroptosis and the stability of SLC7A11, a key component of the cystine-glutamate antiporter related to ferroptosis regulation." (PMID 34249910, 2021). "We recently demonstrated the utility of the tumour explant model to test the therapeutic effects of inhibiting SLC7A11 using either an siRNA-nanomedicine or a clinical-grade SLC7A11 inhibitor, sulfasalazine." (PMID 34067833, 2021). "In this section, we will discuss how SLC7A11-mediated ferroptosis suppression contributes to tumor development in the context of several tumor suppressors and oncogene pathways." (PMID 33000412, 2021). "Accumulating evidence has shown that SLC7A11 is overexpressed in multiple cancers and can promote tumor progression by retarding ferroptosis, leading to metabolic reprogramming." (PMID 34761566, 2021). "Silencing of SLC7A11 expression using our siRNA nanoparticle in patient derived PDAC explants demonstrated potent anti-tumour and anti-stromal effects, and similar results were observed with sulfasalazine treatment of the patient explants." (PMID 34067833, 2021). "Oxidative stress or similar circumstances, function to stabilize and activate NRF2 in the cell nucleus, regulating downstream gene transcription (including SLC7A11); this amplifies glutamate secretion, thereby affecting the tumor microenvironment." (PMID 34446045, 2021). "The tumor suppressor BAP1 is an H2A deubiquitinating enzyme that can inhibit the expression of SLC7A11 by reducing H2A ubiquitination (H2Aub) on the SLC7A11 promoter and then exert its antitumor effect by regulating ferroptosis." (PMID 33574983, 2021). "SLC7A11 expression is related to tumor invasion and metastasis via affecting the redox status or exporting glutamate in the tumor microenvironment." (PMID 34249928, 2021). "MiR-375 acts as a tumor-suppressive miRNA that reduces GC cell stemness primarily via triggering SLC7A11-dependent ferroptosis." (PMID 34805143, 2021). "While most studies have focused on SLC7A11-mediated cystine import, this study suggests that SLC7A11-mediated glutamate export can cross-talk with and modulate tumor immune systems, which in turn influence tumor growth and response to cancer therapies." (PMID 33000412, 2021). "SLC7A11 belongs to the glutamate/cystine antiporter solute carrier family, also known as xCT, and plays a variety of roles in the regulation of tumor growth, invasion, metastasis, and unfavorable prognosis." (PMID 34790572, 2021). "As expected, the expression of miR-382-5p was enhanced and SLC7A11 expression was reduced in the tumor tissues of lidocaine-treated mice compared with that in control group." (PMID 34122108, 2021). "For example, Beclin-1, which is involved in autophagy induction and tumor suppression, was recently identified as a novel solute carrier family 7 member 11 (SLC7A11)/system XC--binding protein." (PMID 33807637, 2021). "Genetic depletion of SLC7A11 or pharmacological inhibition of its function increases tumor cell sensitivity to the proteasome inhibition." (PMID 33401748, 2021). "Further in vivo experiments revealed that SLC7A11 knockdown indeed suppressed the tumor-initiating ability, stem cell frequency of GC cells, and metastatic capacity." (PMID 34090492, 2021).
tumor (continued). "Evidence suggests that the deubiquitinase OTUB1, usually overexpressed in cancers, replicates the ferroptosis process and promotes tumor development by stabilizing the cystine transporter SLC7A11." (PMID 34568341, 2021). "In summary, these data suggested that METTL14 performed a tumour‐suppressive function via targeting SLC7A11 in an m6A‐dependent manner in HCC." (PMID 34609072, 2021). "Our results indicate that ESR1 promotes SLC7A11 transcription to resistance ferroptosis and cytotoxic stress, thereby promoting tumor malignancy." (PMID 35252218, 2021). "It has been reported that CD44, a cancer stem cell marker, positively regulates OTUB1-SLC7A11 pathway and promotes SLC7A11 protein stability for tumor growth." (PMID 34485285, 2021). "It was further shown that genetic ablation or pharmacological inhibition of SLC7A11 markedly attenuates oncogenic KRAS-induced tumor growth in xenograft models." (PMID 33000412, 2021). "Subsequent qRT-PCR analysis also showed that the expression level of CD44, DPP4 and SLC7A11 in ccRCC samples are significantly higher than that in paired non-tumor samples." (PMID 34370716, 2021). "Immunotherapy-activated CD8+ T cells secreted interferon gamma (IFNγ), and then downregulated SLC7A11 in tumor cells and finally promoted cancer cell lipid peroxidation and ferroptosis." (PMID 34722530, 2021). "To support our assumption, we further compared the differential expression of SLC7A11 between human normal and tumor tissues using TCGA data." (PMID 34938318, 2021). "SLC7A11 strongly interacted with 42 autophagy genes as a ceRNA by sponging miRNAs in 32 tumor types." (PMID 34790572, 2021). "CD8+ T cell-derived IFN-γ downregulated the expression of SLC3A2 and SLC7A11 by inhibiting its transcription, thus promoting lipid peroxidation and ferroptosis in tumor cells." (PMID 34764976, 2021). "Several reports have highlighted the critical role of cysteine uptake, specifically in its oxidised form (cystine) via the cystine/glutamate exchanger SLC7A11, which supports tumour initiation and progression in PDAC." (PMID 34588983, 2021). "Combination of TPL with erastin, an inhibitor of SLC7A11, exerts robust synergistic effect in suppression of tumor survival in vitro and in a nude mice model." (PMID 34108030, 2021). "The SLC7A11 mRNA expression was extremely upregulated in tumor tissues compared with normal tissues." (PMID 35252218, 2021). "SLC7A11 was found to be expressed at high levels in tumor samples from KICH, KIRC, and KIRP, with upregulation of HMOX1 occurring in KIRC and KIRP." (PMID 35360452, 2021). "Knockout or knockdown of SLC7A11 markedly suppressed the growth, survival, and tumor formation of cancer cells by inducing ferroptosis." (PMID 34722530, 2021). "We recently demonstrated the utility of the ex vivo tumour explant model to test therapeutic inhibition of an amino acid transporter SLC7A11 using an siRNA nanoparticle and a clinical-grade pharmacological inhibitor, sulfasalazine." (PMID 34067833, 2021). "After acetylating three lysines (K117R, K161R, and K162R), the mutant gene TP533KR is able to induce ferroptosis and suppress tumor growth by inhibiting SLC7A11 and activating ALOX12 expression." (PMID 34235152, 2021). "Correspondingly, considerable interest has been directed toward understanding the role and regulatory mechanisms of SLC7A11 in ferroptosis and tumor biology as well as therapeutically targeting SLC7A11 in cancer therapy." (PMID 33000412, 2021).
tumor (continued). "We observed enhanced SLC7A11 mRNA expression in tumor tissue compared to adjacent healthy tissue, while mRNA of GCLM and GLS remained unaltered." (PMID 34069743, 2021). "Interferon-γ is secreted by CD8+ T cells, leading to the downregulation of the expression of SLC7A11 of tumor cells, decline in levels of intracellular cystine, and prompting ferroptosis." (PMID 34178024, 2021). "In conclusion, compared with SLC7A11-low tumor samples, cancers with higher SLC7A11 expression demonstrated decreased anti-cancer immunity, enhanced metabolic activity, and promoted cell division." (PMID 34938318, 2021). "The deubiquitinase OTUB1 is often overexpressed in human cancers, and by stabilizing the cystine transporter SLC7A11, it replicates the ferroptosis process of cancer cells and promotes tumor development." (PMID 33574983, 2021). "The latest literature reported that CD8 + T cells downregulated the expression of SLC3A2 and SLC7A11 to promote tumor cell lipid peroxidation and ferroptosis." (PMID 34475496, 2021). "Univariate analysis revealed that NRF2 nuclear expression and SLC7A11 expression, sex, tumor location, tumor length, T stage, lymph node and distant metastasis, and TNM stage were all associated with OS; conversely, age, alcohol and smoking history were not." (PMID 34446045, 2021). "In order to link the expression of SLC7A11 to the presence of hLcn-2 in tumor tissue, we correlated SLC7A11 mRNA expression to hLcn-2 levels and found a significant association between these two parameters." (PMID 34069743, 2021). "The paper reported that CD8 + T cells downregulated the expression of SLC3A2 and SLC7A11 to promote tumor cell lipid peroxidation and ferroptosis." (PMID 34475496, 2021). "Recently, SLC7A11 was also reported to be involved in the sensitivity to the histone deacetylase inhibitors; thus, the pharmacological blockade of SLC7A11 not only inhibits tumor growth, but also reverses resistance to certain drugs." (PMID 34573287, 2021). "Our findings revealed that certain FRGs (CISD1, ATP5MC3, PGD, SLC7A11, ACSL3, and FANCD2) are significantly upregulated in LUAD and that their elevated expression is associated with both advanced tumor stage and unfavorable prognosis." (PMID 35320929, 2021). "BAP1 induces ferroptosis by inhibiting cystine uptake and glutathione synthesis based on SLC7A11 inhibition, thereby inhibiting tumor development." (PMID 34616431, 2021). "As a particular SMG of C1, BAP1 has been certified to block cystine uptake by inhibiting the expression of SLC7A11, leading to lipid peroxidation and ferroptosis, thereby inhibiting tumor progression." (PMID 33738257, 2021). "They found that interferon gamma (IFNγ) released from CD8+ T cells downregulated the expression of SLC3A2 and SLC7A11, impaired the uptake of cystine by tumour cells, and promoted ferroptosis." (PMID 34858857, 2021). "By analyzing the gene expression data of immune markers in the TIMER database, we investigated the association between the levels of SLC7A11, GPX4, and AIFM2 and the status of tumor-infiltrating immune cells in ESCA, HNSC, COAD, READ, STAD, and LUAD." (PMID 34722530, 2021). "As further discussed in later sections, some of these SLC7A11 regulators also play important roles in cancer biology, and their dysregulation in cancer can lead to ferroptosis resistance and tumor formation." (PMID 33000412, 2021).
tumor (continued). "IFN-γ released from immunotherapy-activated CD8+ T cells downregulates SLC3A2 and SLC7A11 expression, and increases tumor cell lipid peroxidation and ferroptosis, which ultimately improves anti-tumor efficacy of immunotherapy." (PMID 33815361, 2021). "Mechanistically, SLC7A11 strongly regulated cell autophagy as a competing endogenous RNA (ceRNA) based on pan-cancer analyses of 32 tumor types." (PMID 34790572, 2021). "The CIBERSORT algorithm and single‐sample gene set enrichment analysis (ssGSEA) method were applied to evaluate the effects of SLC7A11 on the tumor immune microenvironment (TIM)." (PMID 34761566, 2021). "Recent studies revealed that SLC7A11 overexpression promotes tumor growth partly through suppressing ferroptosis, a form of regulated cell death induced by excessive lipid peroxidation." (PMID 33000412, 2021). "To address if SLC7A11 inhibition can mimic the tumour‐suppressive function of METTL14, we first detected the effect of SLC7A11 knockdown on ferroptosis induction." (PMID 34609072, 2021). "Recent studies have also shown that SLC7A11 overexpression inhibits ROS-induced ferroptosis and leads to a significant abrogation of the tumor suppression function of p533KR, which can mediate senescence, apoptosis, and cell-cycle arrest." (PMID 31941443, 2020). "For example, the GSH synthesis in tumor cells can be increased significantly during oxidative stress by upregulating the cystine/glutamate antiporter SLC7A11 and glutamate cysteine ligase modifier subunit (GCLM)." (PMID 32595640, 2020). "In the current investigation, we address this question in multiple tumor cell lines and identified xCT (SLC7A11) as a putative predictor for resistance against cold plasma treatment in tumor cells." (PMID 31931281, 2020). "p533KR, an acetylation-defective mutant, represses the transcription of SLC7A11 to induce ferroptosis under higher ROS levels in tumor tissue, subsequently inhibiting tumor growth." (PMID 32908642, 2020). "IFN-γ released by activated CD8+ T cells in cancer immunotherapy inhibits the expression of SLC7A11 to enhance sensitivity to ferroptosis inducers, thereby limiting tumor proliferation." (PMID 32908642, 2020). "The expression level of ABCA1 and SLC7A11 has been evaluated in three independent tumor nodules treated with DMSO or fendiline/cisplatin; results showed a significant inhibition of their transcription." (PMID 33182713, 2020). "Of note, the mRNA levels of Arg1, Slc7a8 and Slc7a11 were substantially higher in tumor than in splenic F4/80+ cells." (PMID 32396064, 2020). "Cystine, the oxidized dimer of cysteine, can also be absorbed from the tumor microenvironment by xCT (SLC7A11), which is a heterodimeric cystine–glutamate antiporter, where overexpression is associated with overall poor survival in ccRCC." (PMID 31357507, 2019).
tumor (continued). "Although this regulation occurs in normal cells, in tumor cells, other mediators of SLC7A11 appear to predominate in the regulation of this gene." (PMID 29695998, 2018). "The evaluating level of SLC7A11 reversed the tumor‐suppressing effect of miR‐375 on cell proliferation, migration, invasion, mitosis and apoptosis, which further confirmed the important role of miR‐375/SLC7A11 axis on the progression of OSCC." (PMID 28627030, 2017). "To corroborate these findings in vivo, we found that endogenous SLC7A11 expression correlated closely with tumour response to APR-246 in eight patient-derived xenograft and cell line models." (PMID 28348409, 2017). "In FLO-1 xenografts, we found that SLC7A11 knockdown significantly enhanced the anti-tumour activity of APR-246, leading to synergistic reduction of intratumoral GSH levels and improved animal survival." (PMID 28348409, 2017). "Collectively, these experiments suggest that glutaminase dependence in culture for many cancer cells derived from various tumor types will be strongly influenced by both environmental cystine and xCT/SLC7A11 expression." (PMID 28826492, 2017). "Similarly, hypoxia in GBM induced by anti-VEGF antibody exposure is shown to lead to dysfunctional glutamate/cystine antiporter (SLC7A11/xCT) activity of tumor cells." (PMID 40058234, 2025). "In lung cancer cells and animal models, the combination of curcumin and quercetin effectively advances the ferroptosis process by modulating the miR-520a-5p/SLC7A11 signaling pathway, which inhibits circFOXP1 expression, thereby suppressing tumor growth, migration, and invasion." (PMID 41515171, 2025). "We further confirmed by western blotting that IKE-treated TIPE2−/− tumor MDSCs profoundly enhanced the key ferroptosis defense proteins SLC7A11 and GPX4, but immensely lowered the main lipid peroxidation trigger protein ACSL4 when compared to IKE-treated WT tumor MDSCs." (PMID 39851538, 2025). "Moreover, in vivo experiments have shown that the deletion of the SLC7A11 gene in T cells has no clear impact on their antitumor response, while the knockout of the SLC7A11 gene in tumor cells can enhance the efficacy of tumor immunotherapy." (PMID 41293169, 2025). "In addition, as the SLC7A11 is expressed on one-third of triple-negative breast tumors in vivo, sulfasalazine was proven to suppress tumor growth of triple-negative tumors." (PMID 39569390, 2025). "Restoring its expression or inhibiting antagonist molecules such as CST1 and SLC7A11 could be an effective strategy for suppressing tumor progression." (PMID 40076805, 2025). "Additionally, TRIM21-mediated METTL3 degradation induces ferroptosis by disrupting SLC7A11 mRNA stability and inhibits tumor progression during anti–PD-1 therapy." (PMID 40175350, 2025). "Thus, tumor cell depends more on SLC7A11 in acquiring cysteine and keep redox homeostasis than normal tissues." (PMID 40855044, 2025).